CLDN18 (claudin 18)
Description:
Involved in alveolar fluid homeostasis via regulation of alveolar epithelial tight junction composition and therefore ion transport and solute permeability, potentially via downstream regulation of the actin cytoskeleton organization and beta-2-adrenergic signaling (By similarity). Required for lung alveolarization and maintenance of the paracellular alveolar epithelial barrier (By similarity). Acts to maintain epithelial progenitor cell proliferation and organ size, via regulation of YAP1 localization away from the nucleus and thereby restriction of YAP1 target gene transcription (By similarity). Acts as a negative regulator of RANKL-induced osteoclast differentiation, potentially via relocation of TJP2/ZO-2 away from the nucleus, subsequently involved in bone resorption in response to calcium deficiency (By similarity). Mediates the osteoprotective effects of estrogen, potentially via acting downstream of estrogen signaling independently of RANKL signaling pathways (By similarity). [Isoform A1]: Involved in the maintenance of homeostasis of the alveolar microenvironment via regulation of pH and subsequent T-cell activation in the alveolar space, is therefore indirectly involved in limiting C.neoformans infection. [Isoform A2]: Required for the formation of the gastric paracellular barrier via its role in tight junction formation, thereby involved in the response to gastric acidification.
Synonyms: SFTA5; SFTPJ
Tractability: Antibody: a drug acting on it is in phase 2 or 3 trials; UniProt places it where antibodies can reach, with medium confidence; UniProt predicts a signal peptide or a membrane-spanning region; its Gene Ontology location is reachable by antibodies, with medium confidence.
Gene: Protein-coding gene on chromosome 3 (137,998,735 to 138,033,655, forward strand). Ensembl gene ENSG00000066405.
Subcellular location: Cell junction, tight junction; Cell membrane; Cell junction, tight junction (Isoform A1); Cell junction, tight junction (Isoform A2); Lateral cell membrane
Subcellular location (Human Protein Atlas): Cell Junctions
Pathways (Reactome):
Cell-Cell communication: Tight junction interactions
Gene Ontology:
Molecular function: protein binding; identical protein binding; structural molecule activity
Biological process: calcium-independent cell-cell adhesion; cellular response to estrogen stimulus; epithelial cell proliferation; epithelial fluid transport; lung alveolus development; negative regulation of protein localization to nucleus; organ growth; tight junction assembly; tight junction organization; response to ethanol
Cellular component: bicellular tight junction; cell-cell junction; lateral plasma membrane; plasma membrane; membrane; tight junction
Genetic constraint (gnomAD): Loss-of-function variants: 14 observed, 18.57 expected, observed/expected ratio (o/e) 0.75, 90% interval 0.5 to 1.18. The upper end of that interval is the gene's LOEUF score, 1.18, which puts it in group 5 of 6, group 1 being the genes least tolerant of losing a copy. Missense variants: 239 observed, 291.02 expected, observed/expected ratio (o/e) 0.82, 90% interval 0.74 to 0.91. Synonymous variants: 107 observed, 119.82 expected, observed/expected ratio (o/e) 0.89, 90% interval 0.76 to 1.05.
Homologues: Orthologues: chimpanzee CLDN18 (100% identical), macaque CLDN18 (99% identical), dog CLDN18 (94% identical), mouse Cldn18 (89% identical), guinea pig CLDN18 (89% identical), rabbit CLDN18 (85% identical), pig CLDN18 (85% identical), rat Cldn18 (84% identical), tropical clawed frog cldn18 (75% identical), zebrafish cldn18 (30% identical). Paralogues in human: CLDN1 (28% identical), CLDN3 (28% identical), CLDN4 (28% identical), CLDN6 (27% identical), CLDN7 (27% identical), CLDN10 (26% identical), CLDN14 (26% identical), CLDN15 (26% identical), CLDN19 (26% identical), CLDN9 (25% identical), CLDN17 (25% identical), CLDN24 (24% identical), and 10 more.
Diseases named in the same sentence as CLDN18 in open-access papers:
CLDN18 is named in the same sentence as 121 diseases in open-access papers, as found by Europe PMC text mining. Sharing a sentence is not in itself a finding about the gene and the disease. The quoted sentences say what the papers report.
gastric cancer (116 papers, 2006 to 2026). A primary or metastatic malignant neoplasm involving the stomach. "BACKGROUND: Zolbetuximab for CLDN18.2-positive advanced gastric cancer frequently causes chemotherapy-induced nausea and vomiting (CINV), particularly during the first infusion." (PMID 41943132, 2026). "The number and geographic location of participating institutes do not provide a complete overview of the expected diagnostic landscape for CLDN18.2 testing in gastric cancers; hence, the results cannot be generalized completely." (PMID 40579565, 2025). "The prevalence of CLDN18-ARHGAP fusion mutations in gastric cancer has been reported to be about 20%20." (PMID 38704377, 2024). "This analysis revealed processes active in each subclone, such as the de-regulation of CLDN18, previously reported in gastric cancer, and DHRS2, also associated with gastric carcinogenesis." (PMID 37917660, 2023). "The survival outcome meta-analysis of the CLDN18-ARHGAP fusion gene showed that it was associated with overall survival outcomes in gastric cancer (HR, 2.03, 95% CI 1.26-3.26, P < 0.01, random-effects)." (PMID 32983960, 2020). "In summary, we identified a useful pair of target molecules, CDH17 and CLDN18, to aid in the comprehensive detection and localization of gastric cancer metastases in vivo to overcome challenges associated with intratumoral heterogeneity." (PMID 27580354, 2016). "Down-regulation of claudin-18 is associated with the proliferative potential at the invasive front of gastric cancer, suggesting that it has a pivotal role in gastric cancer progression." (PMID 24073219, 2013). "Furthermore, exploring mechanisms underlying gastric cancer patients with low CLDN18.2 expression is essential for devising targeted therapies and combined treatment strategies involving conventional radiotherapy, chemotherapy, and others." (PMID 37833730, 2023). "Recently, Yu Takahashi and colleagues demonstrated that nuclear expression of CLDN18 was independently associated with gastric cancers and could be a novel diagnostic marker for gastric cancer." (PMID 35861118, 2023). "For example, for CLDN18, gene amplification mainly occurs in lung squamous, cervical, oesophageal, head and neck, and ovarian cancer, whereas mutation is predominately found in uterine cancer, and gene fusion is predominately found in stomach cancer." (PMID 34354941, 2021). "MTAP-ANRIL fusion has been reported in melanoma and CLDN18-ARHGAP26 in gastric cancer, the latter promoting loss of the epithelial phenotype in gastric cancer.TMPRSS2 fusions may be defining markers for prostate cancer." (PMID 31007851, 2019). "Given that poorly cohesive cell growth is characteristic of DGC, these findings collectively suggest that relatively high prevalence of the CLDN18-ARHGAP26 fusion in young DGC patients underlies the strong enrichment of diffuse histology observed in early-onset gastric cancer." (PMID 30361512, 2018). "Together, these results indicate that CDH17 and CLDN18 are useful target molecules; moreover, their coupling can aid in the comprehensive detection and localization of gastric cancer metastases in vivo to overcome challenges associated with intratumoral heterogeneity." (PMID 27580354, 2016). "For example, claudin-1 is associated with colon cancer prognosis, claudin-18 is related to gastric cancer (GC) prognosis, and claudin-10 is relevant to hepatocellular carcinoma prognosis." (PMID 38511141, 2024). "The presence of the CLDN18-ARHGAP26 mutation has been shown to facilitate the progression and metastasis of gastric cancer (GC) through the loss of CLDN18 function and the acquisition of ARHGAP26 functions." (PMID 38704377, 2024). "While the results may seem contradictory, it was interesting to note that the reported downregulation of claudin-18.2 expression occurred more frequently in the intestinal variant than in the diffuse variant of gastric cancers (significant expression in 46% versus 75%)." (PMID 37627123, 2023).
gastric cancer (continued). "We evaluated the clinical significance of CLDN18.2 and fibroblast growth factor receptor 2b (FGFR2b) expression in patients with locally advanced gastric cancer treated with neoadjuvant therapy." (PMID 42121981, 2026). "CMG901 is being evaluated in a phase III trial (NCT06346392) for advanced CLDN18.2-positive gastric cancer and GEJ adenocarcinoma." (PMID 41019366, 2025). "Cldn18 is specifically expressed in gastric epithelial cells and represents a novel therapeutic target in human gastric cancer, making this an appropriate driver for gastric-specific genetic manipulation." (PMID 40673273, 2025). "Zolbetuximab received approval in September 2024 from the European EMA and in October 2024 from the US FDA as a first-line treatment for HER2-negative, CLDN18.2-positive advanced gastric cancer." (PMID 41614808, 2025). "Conversely, Claudin-18 is highly expressed in malignant tumors, particularly in gastric cancer, making it a better target." (PMID 39813112, 2025). "In gastric cancer patients, CLDN18.2-staining intensity is decreased in peritoneal metastasis compared with primary lesion." (PMID 41164107, 2025). "While CLDN18.2 remains the frontrunner, the inherent heterogeneity of gastric cancer necessitates a broader spectrum of therapeutic targets to mitigate the risk of antigen escape." (PMID 41614808, 2025). "For HER2-negative gastric cancers, immune checkpoint inhibitors (e.g., nabulizumab) or zolbetuximab-clzb (which requires CLDN18.2 positivity) in combination with chemotherapy are recommended." (PMID 40909948, 2025). "This study aimed to investigate FGFR2b expression and gene amplification in matched primary tumors and PD tissues from gastric cancer patients, and to evaluate their association with established biomarkers including HER2, CLDN18, and PD-L1." (PMID 40884562, 2025). "The findings of the two studies provided compelling evidence that CLDN18.2 is the third key biomarker in first-line gastric cancer treatment, following HER2 and PD-L1." (PMID 41614808, 2025). "When gastric cancer is classified into four molecular subtypes, the fusion of CLDN18 with ARHGAP can be observed specifically in the genomically stable subtype." (PMID 40936686, 2025). "Another study demonstrated that gastric cancer patients with high CLDN18.2 expression (≥40%) exhibited a more complex immune microenvironment." (PMID 40900784, 2025). "From a therapeutic perspective, CLDN18.2 clinical trials in gastric cancer have focused on IMAB362 (also known as zolbetuximab) is a chimeric antibody that selectively binds to CLDN18.2-expressing tumor cells with minimal off-target effects." (PMID 40687428, 2025). "As already stated for gastric cancer, only tumor cells with perceptible and convincing linear immunoreactivity for CLDN18 should be considered positive." (PMID 40835751, 2025). "This study investigated the prevalence of CLDN18.2 expression in patients with stages II-IV gastric cancer or gastroesophageal junction adenocarcinoma and its correlation with clinicopathologic features and other crucial biomarkers." (PMID 39306800, 2025). "Both studies included the enrollment of patients with HER2-negative, CLDN18.2-positive (moderate or strong membrane staining in ≥75% of tumor cells by IHC) advanced gastric cancer receiving first-line chemotherapy." (PMID 41614808, 2025). "A 41-year-old woman with metastatic Claudin-18.2-positive gastric cancer was treated with ZOL in combination with chemotherapy." (PMID 40792275, 2025). "Due to its specific expression in gastric cancer, CLDN18 has emerged as a potential therapeutic target." (PMID 40936686, 2025). "In Japan, zolbetuximab is approved in combination with chemotherapy for patients with HER2-negative, CLDN18.2-positive, unresectable, advanced or recurrent gastric cancer." (PMID 40579565, 2025).
gastric cancer (continued). "Abnormal expression of Claudin-18 is frequently observed in the development and progression of various primary malignant tumors, including gastric cancer, pancreatic cancer, oesophageal cancer, ovarian cancer and non-small cell lung cancer." (PMID 39813112, 2025). "Zolbetuximab, the first CLDN18.2-directed therapy, has improved survival in advanced gastric cancer, leading to growing interest in this pathway." (PMID 41374966, 2025). "This case report provides the first clinical evidence that CLDN18.2-targeted therapy with LM302 combined with metastasectomy can be effective in young patients with refractory gastric cancer." (PMID 40900784, 2025). "This systematic review aimed to explore the relationship between CLDN18.2 and the tumor microenvironment in gastric cancer." (PMID 40647419, 2025). "Supporting reliable testing for this biomarker is essential to ensure appropriate identification and implementation of treatment targeting CLDN18.2 in patients with gastric cancer." (PMID 40579565, 2025). "Treatment was started with zolbetuximab plus 5-fluorouracil/leucovorin/oxaliplatin (FOLFOX), which is typically used for CLDN18.2-positive gastric cancer, resulting in a partial response." (PMID 41256328, 2025). "This case report presents the treatment process of a young female patient with refractory gastric cancer who achieved complete remission through CLDN18.2-targeted therapy with LM302 combined with metastasectomy." (PMID 40900784, 2025). "Several studies have confirmed that CLDN18 expression is significantly downregulated in gastric cancer relative to normal mucosa." (PMID 40687428, 2025). "When using the threshold established for gastric cancer (≥ 75% of tumor cells expressing 2 +/3 + staining), the prevalence of CLDN18 positivity in PDAC is around 30% globally." (PMID 40835751, 2025). "Claudin 18.2 (CLDN18.2), an isoform of claudin 18 (CLDN18), is a biomarker and drug target for gastric cancer." (PMID 40579565, 2025). "The modality of CLDN18 immunohistochemical testing has been recently codified in a recommendation paper for gastric cancer." (PMID 40835751, 2025). "Overexpressing CAD or mutating Asp1371 to block caspase-3 cleavage confers chemoresistance in xenograft and Cldn18-ATK gastric cancer models." (PMID 40442064, 2025). "Based on the results of the Spotlight Study and the Glow Study, approximately 33–38% of gastric carcinomas and transitional cancers are positive for CLDN18.28,14." (PMID 40775258, 2025). "The efficacy and safety of zolbetuximab underscored the potential of CLDN18.2 as an encouraging therapeutic target for gastric cancer." (PMID 39227365, 2024). "CLDN18.2-targeted therapies have shown promising efficacy against gastric cancers that express high levels of CLDN18." (PMID 38724721, 2024). "The CLDN18-ARHGAP fusion gene is an oncogenic driver newly discovered in gastric cancer which occurs frequently." (PMID 39164472, 2024). "According to our own gastric cancer cohort, CLDN18.2-positive patients had higher stage, poorer prognosis, and more CAFs infiltrated into tumors than CLDN18.2-negative patients." (PMID 38200591, 2024). "This study demonstrated that the positive rate of CLDN18.2 was higher in patients with EBV-positive or PD-L1-positive gastric cancer, whereas it was lower in HER2-positive patients." (PMID 39555091, 2024). "Owing to the limited number of specimens analyzed in this study, further studies are required to determine the optimal biopsy procedure for assessing CLDN18 expression in gastric cancer." (PMID 38724721, 2024). "More recently, yet another meta-analysis, comprising six studies and involving 2440 gastric cancer (GC) patients, provided a well-defined scoring system for CLDN18.2 staining." (PMID 38339430, 2024). "In this study, we aimed to investigate the expression characteristics of CLDN18.2 in gastric cancer clinical staging and its correlation with other pathological molecular characteristics." (PMID 38200591, 2024).
gastric cancer (continued). "Mechanistically, gastric cancer cells with CLDN18-ARHGAP fusion activate PI3K/AKT-mTOR-FAS signaling, which enhances free fatty acid production of gastric cancer cells to favor the survival of Treg cells." (PMID 39164472, 2024). "Our study for the first time reveals that CLDN18.2-targeted ADC can trigger cytoprotective autophagy in gastric cancer, filling this knowledge gap." (PMID 39227365, 2024). "Recent trials show that Zolbetuximab, a CLDN18.2-targeting drug, works well with chemotherapy for CLDN18.2-positive gastric cancer." (PMID 38339430, 2024). "CLDN18-ARHGAP fusion gene of gastric cancer generates an immunogenic neoantigen, which induces neoantigen reactive T cells specifically targeting and eliminating gastric cancer cells with CLDN18-ARHGAP fusion gene." (PMID 39164472, 2024). "In gastric cancers, CLDN18 has been shown to be reduced, while its upregulation has been reported in pre-neoplastic conditions such as Barrett’s esophagus, mucinous cystic neoplasms, and intraductal papillary mucinous neoplasms." (PMID 38540693, 2024). "Our findings underscored the potential of combining CLDN18.2-directed ADCs with autophagy inhibitors as a novel and encouraging therapeutic approach to treat gastric cancer." (PMID 39227365, 2024). "Because of the limited information regarding CLDN18.2 status in PD, we analyzed PD-positive gastric cancers for CLDN18 status in both primary and PD, along with HER2 and PD-L1 combined positive score (CPS)." (PMID 38724721, 2024). "Downregulation of claudin proteins has been reported in many cancer types, including claudin-2 and claudin-6 in breast cancer and claudin-18 in gastric cancer." (PMID 38540693, 2024). "For instance, the anti-CLDN EPR19202 kit (Abcam, Cambridge, UK), which is specific for the CLDN 18.2 isoform, was used in Leica Bond-Max Autostainer for CLDN18 expression detection of esophageal and gastric cancer." (PMID 38339430, 2024). "Currently, the CLDN18.2 immunohistochemical examination has been incorporated into the routine postoperative pathological evaluation of gastric cancer patients at our research center." (PMID 37833730, 2023). "CLDN18-ARHGAP26 fusion gene is one of the most frequent somatic genomic rearrangements in gastric cancer, especially in the genomically stable subtype." (PMID 36969060, 2023). "A previous study suggested that downregulated CLDN18 expression in gastric cancer cells correlates with increased cellular proliferation and epithelial-to-mesenchymal transition, both of which are associated with invasion and metastasis." (PMID 37629433, 2023). "Limited clinical research currently exists on CLDN18.2 expression in gastric cancer peritoneal metastasis." (PMID 37833730, 2023). "CLDN18 is an adhesion molecule extensively expressed in the cytoplasmic membrane of gastric epithelial cells in normal and gastric cancer tissue." (PMID 35861118, 2023). "In this review, we focused on established (PD-L1, HER2, MSI) and emerging biomarkers (FGFR2, CLDN18.2) in gastric cancer, their clinical significance, detection methods, limitations, and molecular agents that target these biomarkers." (PMID 37510761, 2023). "Kaplan‒Meier survival curves were utilized to analyse the effect of CLDN18.2 on gastric cancer survival rates." (PMID 37582713, 2023). "Diffuse-type and, in particular, the GS molecular subtype of gastric cancer are also enriched for CLDN18-ARHGAP fusions, which seem to be mutually exclusive with RHOA and CDH1 mutations." (PMID 36812376, 2023). "Previous studies have shown that CLDN18 is significantly downregulated in gastric cancer tissues, but is elevated in patients with bone metastasis." (PMID 37438735, 2023). "According to reports, genomically stable gastric cancers frequently have chromosomal rearrangements of the CLDN18 and ARHGAP genes, primarily CLDN18-ARHGAP26/6 fusions." (PMID 36620607, 2022).